GAS6 (growth arrest specific 6)
Diseases named in the same sentence as GAS6 in open-access papers (continued):
Sharing a sentence is not in itself a finding about the gene and the disease.
Obesity (14 papers, 2013 to 2025). Accumulation of substantial excess body fat. "Obesity is an independent risk factor for cardiovascular disease, and further investigation into the association between Gas6, BMI, and coronary artery disease is needed." (PMID 39684449, 2024). "The expression of GAS6 in the hyperplasia synovial tissues from obesity-associated OA in the present study was down-regulated and accompanied by an increase in M1 macrophage polarization." (PMID 37144868, 2023). "Immunofluorescence (IF) staining analysis indicated that macrophage release of GAS6 expressed in both human and mouse normal synovial tissues tended to be diminished, especially in obesity-associated OA." (PMID 37144868, 2023). "Enhanced M1-polarized macrophages in obese synovium decreased GAS6 secretion, impairing efferocytosis for synovial ACs and causing synovial hyperplasia and obesity-associated OA development." (PMID 37144868, 2023). "Down-regulation of GAS6 by M1 macrophages resulted in impaired efferocytosis for synovial ACs, causing synovial hyperplasia and obesity-associated OA development." (PMID 37144868, 2023). "The present study explored the association between synovial macrophage polarization types and the GAS6/Axl pathway in obesity-associated OA." (PMID 37144868, 2023). "We also recently confirmed the close association between Gas6 and obesity and Gas6 and inflammation in both adults and adolescents." (PMID 26284522, 2015). "Taken together, GAS6 signaling is important for the development of obesity, but the underlying mechanism remains to be elucidated." (PMID 25954309, 2015). "Recent studies in animal models have shown that Gas6/TAM signaling plays an important role in pathophysiological mechanisms underlying obesity-related inflammation and insulin resistance (IR)." (PMID 26284522, 2015). "Growth arrest-specific 6 (Gas6), a vitamin K-dependent protein, has been implicated in systemic inflammation, obesity, and insulin resistance (IR)." (PMID 26284522, 2015). "In this review, we summarize the results of current studies from clinical and basic research to elucidate the possible role of GAS6 signaling in obesity and associated disorders." (PMID 25954309, 2015). "In particular, GAS6/Axl signaling is important in the mechanism underlying inflammation that resulted from obesity and associated complications." (PMID 25954309, 2015). "Several recent clinical studies have shown that GAS6 signaling significantly contributes to the development of obesity and associated inflammation." (PMID 25954309, 2015). "The protective role of the AA genotype of GAS6 rs8191974 against the developing childhood obesity and obesity-associated complications requires further study." (PMID 24696684, 2014). "In this study, GAS6 is further implicated as a candidate susceptibility gene for obesity and systemic inflammation." (PMID 24696684, 2014). "Together, these findings suggest that the GAS6 rs8191974 polymorphisms play an important role in the development of obesity and obesity-associated complications (e.g., type 2 diabetes, cerebrovascular, and cardiovascular diseases)." (PMID 24696684, 2014). "Furthermore, elevated levels of Gas6 have been associated with obesity, markers of endothelial dysfunction, and atherogenesis in women only." (PMID 39684449, 2024). "Therefore, targeting macrophage-associated ectocytosis or intraarticular injection of GAS6 is a potential therapeutic strategy for obesity-related OA." (PMID 38660308, 2024). "At the same time, since obesity can also cause many complications, growth arrest-specific 6 (GAS6) can restore the phagocytic ability of macrophages and reduce the level of TUNEL and Caspase-3 positive cells, maintain cartilage thickness and prevent the progression of obesity-related arthritis." (PMID 38660308, 2024). "Therefore, targeting macrophage-associated efferocytosis or intra-articular injection of GAS6 is a potential therapeutic strategy for obesity-associated OA." (PMID 37144868, 2023).
Obesity (continued). "Of interest, the deleted region in each of the 7 cases overlaps the obesity-associated gene GAS6." (PMID 29441128, 2018). "Thus, the aim of the present study was to explore the effects of genetic variations of Gas6 on obesity and the risk of developing IR in an Asian population." (PMID 26284522, 2015). "Taken together, it implies that Gas6 signaling may play an important role in the development of obesity, but the exact mechanism of Gas6 and its genetic polymorphisms on adiposity is unknown, and further investigations are needed." (PMID 26284522, 2015). "However, the causal relationship between GAS6 and obesity-related cardiometabolic abnormalities remains controversial." (PMID 25954309, 2015). "The Axl receptor-mediated pathway may play a substantial role in GAS6-mediated inflammatory signaling in states of obesity and associated type 2 diabetes." (PMID 25954309, 2015). "Previous experiments in transgenic mice demonstrate that Gas6 might also induce obesity-associated inflammation via recruiting immune cells into the adipose tissue to producing and secreting proinflammatory cytokines." (PMID 24696684, 2014). "Moreover, the combination of both GAS6 polymorphisms had an additive effect on the development of obesity and obesity-associated inflammation in boys." (PMID 24696684, 2014). "Moreover, the GG genotype of GAS6 rs8191973 or rs8191974 strongly correlates with susceptibility to develop obesity and systemic inflammation in boys." (PMID 24696684, 2014). "This suggests that the Gas6/Axl signaling might play a role in the pathogenesis of obesity-associated systemic inflammation." (PMID 24696684, 2014). "Obesity stimulates synovial macrophage infiltration and M1 polarization, which suppress the secretion of GAS6." (PMID 37144868, 2023). "GAS6 which binds to the TYR03 receptor has previously been associated with cell differentiation in adipocytes and obesity in both humans and mice." (PMID 31170913, 2019). "Our findings implicate many genes previously associated with obesity (e.g. PTBP2, TMEM18, MYT1L, POU3F2, SIM1, SH2B1), and also identified other potentially relevant candidates including TAS1R3, ALOX5AP, and GAS6." (PMID 29441128, 2018). "From a clinical perspective, clarifying the role of GAS6 signaling from bench to clinic will provide great benefit in development of strategies for the prevention and treatment of obesity and its related complications." (PMID 25954309, 2015). "While many studies have focused on the role of GAS6 in inflammation and cancer, only few studies focused on its roles of GAS6 in obesity." (PMID 25954309, 2015). "Gas6/Axl signaling has been shown to be involved in the pathogenesis of obesity and systemic inflammation." (PMID 24696684, 2014). "This genotyping of GAS6 might be suitable for predicting the future progress of obesity and its related complications." (PMID 25954309, 2015). "However, only a few reports have been published regarding the link between GAS6 signaling and the pathogenesis of obesity." (PMID 25954309, 2015). "In the present study, we found that none of the Gas6 genetic SNPs had a positive association with obesity." (PMID 26284522, 2015). "Accordingly, the participation of GAS6 in the progression of obesity remains controversial." (PMID 25954309, 2015). "Since, however, the loss of Gas6, a ligand for both Mer and Axl, also protects mice against HFD-induced obesity, and obesity in humans is associated with increased plasma Gas6 levels, decreasing Gas6 levels by neutralizing antibodies might be a more realistic approach to target obesity." (PMID 39594650, 2024). "Intra-articular injection of GAS6 restored the phagocytic capacity of macrophages, reduced the accumulation of local ACs, and decreased the levels of TUNEL and Caspase-3 positive cells, preserving cartilage thickness and preventing the progression of obesity-associated OA." (PMID 37144868, 2023).
Obesity (continued). "However, no other significant correlations were observed between Gas6 polymorphisms and other indices of IR or obesity." (PMID 26284522, 2015). "However, the association of Gas6 gene variants with obesity, IR, and T2D development has not been explored." (PMID 26284522, 2015). "First, this was a cross-sectional study, as such we might not be able to assess GAS6 polymorphisms on weight dynamics and the development of obesity-associated complications throughout life." (PMID 24696684, 2014). "(A) Immunofluorescence staining for F4/80 (red) and GAS6 (green) in synovial tissue from normal individuals, OA patients without obesity, obese individuals, and OA patients with obesity." (PMID 37144868, 2023). "Collectively, these observations implicate that GAS6 may participate in adipogenesis by regulating cell proliferation and differentiation through TAM receptors and may subsequently affect the development of obesity." (PMID 25954309, 2015). "To date, in-depth studies on the role of the Gas6 gene in obesity and IR are lacking." (PMID 26284522, 2015).
systemic lupus erythematosus (14 papers, 2010 to 2025). An autoimmune multi-organ disease typically associated with vasculopathy and autoantibody production. "For instance, raised concentrations of soluble TAMs associate with lupus, Sjogren's syndrome, and RA; Gas6 is heightened in a multitude of diseases, such as inflammatory autoimmune demyelinating diseases, Alzheimer's disease, and hepatic fibrosis." (PMID 32051695, 2020). "GAS6 and its receptor Axl are known to regulate apoptotic-related inflammation and may be implicated in lupus pathogenesis." (PMID 37144868, 2023). "Conversely, other authors have found lower Gas6 plasmatic concentrations in lupus, Behcet's disease, and inflammatory bowel diseases in comparison with healthy controls." (PMID 32051695, 2020). "Mohan's group demonstrated that combined inhibition with ADAM10 and ADAM17 rescues the unresponsiveness of lupus-prone splenocytes to Gas6." (PMID 31360267, 2019). "A correlation of plasma concentrations of Gas6 and sAxl with disease activity in systemic lupus erythematosus has recently been reported." (PMID 25885003, 2015). "Recent reports indicate that the Gas6/TAM system is also involved in the pathogenesis of systemic lupus erythematosus (SLE), and that Gas6 may correlate in several ways with disease activity in SLE." (PMID 26445266, 2015). "In Systemic Lupus Erythematosus (SLE), vitamin K influences disease activity through GAS6 and its receptor-mediated regulation of inflammation." (PMID 40718363, 2025). "In autoimmune diseases, such as systemic lupus erythematosus (SLE), where impaired clearance of apoptotic cells leads to the release of self-antigens, this triggers an autoimmune response that GAS6 dampens." (PMID 38817615, 2024). "Increased levels of sAxl and sTyro3 have also been found in lupus patient blood, and all three soluble TAMRs can compete for the TAMR ligands Gas6 and protein S to block Mer function." (PMID 24650765, 2014). "GAS6 concentration in SLE has been evaluated by two studies, demonstrating either an increased concentration or similar levels in patients with lupus." (PMID 23497733, 2013). "In systemic lupus erythematosus (SLE) patients, a derangement of the Gas6/TAM system with increased Gas6, sAxl, and sMer plasma concentrations has been correlated with disease activity and with the parameters of renal involvement in SLE patients with lupus nephritis (LN)." (PMID 39057085, 2024). "Higher levels of Gas6 also predict oesophageal varices in patients affected by hepatitis C virus (HCV) liver disease and correlate with disease severity in multiple sclerosis and renal involvement in systemic lupus erythematosus (SLE)." (PMID 32051695, 2020).
glioblastoma (13 papers, 2013 to 2024). The most malignant astrocytic tumor (WHO grade IV). "It has been demonstrated that AXL and/or GAS6 overexpression were associated with a worse prognosis and more aggressive malignancy, as seen, for instance, in glioblastoma patients." (PMID 38391974, 2024). "It has been shown that overexpression of AXL and its ligand Gas6 in glioblastoma (GBM) tissue is associated with reduced time to progression and overall survival time in these patients." (PMID 28881571, 2017). "It has been shown that malignant human gliomas often overexpress AXL and/or GAS6, and that individuals with glioblastoma who have elevated levels of these proteins have a markedly shortened time to tumor growth." (PMID 38391974, 2024). "Corosolic acid 20 μM notably reduced AXL and GAS6 expression in glioblastoma cell lines, also lowering the phosphorylated expression of JAK2, MEK and ERK." (PMID 38391974, 2024). "The activation of many actin-dependent processes by GAS6-AXL signaling has been shown to regulate the invasion of glioblastoma cells, and PI3K is a significant downstream effector of this signaling." (PMID 38391974, 2024). "We and others previously demonstrated co-expression of MERTK and AXL, MERTK and GAS6 (a TAM kinase ligand), and AXL and GAS6 in tumor biopsies from pediatric patients with glioblastoma multiforme." (PMID 27783662, 2016). "GAS6 is overexpressed in glioblastoma, gastric, and ovarian cancers." (PMID 23878800, 2013). "We incubated serum-starved glioblastoma LN229 cells, which we previously used for the identification of AXL interactome, with purified Myc-tagged version of GAS6 (hereafter called GAS6) for various time periods." (PMID 35622156, 2022). "Recently, GAS6/AXL-triggered actin remodeling has been demonstrated to play an important role in driving the invasion and macropinocytosis of glioblastoma cells in a PI3K-dependent manner." (PMID 34831142, 2021). "Gas6 expression was shown in tumor cells of gastric cancer, ovarian cancer and glioblastoma multiforme (GBM), unlike renal cell carcinoma and breast cancer." (PMID 27486820, 2016).
leukemia (12 papers, 2012 to 2025). A malignant (clonal) hematologic disorder, involving hematopoietic stem cells and characterized by the presence of primitive or atypical myeloid or lymphoid cells in the bone marrow and the blood. "In leukemia, GAS6 AS1 binds directly to YBX1, promoting its interaction with MYC and resulting in the activation of MYC target genes associated with leukemia progression." (PMID 40799245, 2025). "Another study found that Gas6 secretion by leukemia was low and Gas6 was mainly produced by bone marrow stroma cells." (PMID 32298237, 2020). "A similar role of Gas6 at the endosteal niche is also demonstrated in leukemia, where Gas6 mediates migration and binding to MerTK, which protects the cancer cells from apoptosis, therefore inducing treatment resistance." (PMID 29642534, 2018). "Gas6 produced by stromal cells promotes the colony forming potential of hematopoietic stem cells and has more recently been identified as an independent poor prognostic factor in AML, implying a role for Gas6 in maintaining the leukemia stem cell population." (PMID 27834816, 2016). "For example, in AML, leukaemia-derived M-CSF and IL-10 instruct stromal cells to secrete Gas6, which is the ligand for the TAM family tyrosine kinase receptor Axl." (PMID 25056697, 2014). "In human leukemia cell lines, continuous Gas6 exposure promoted expression of a partially N-glycosylated form of Mer, a glycoform that developed from de novo partial glycosylation of a newly synthesized protein." (PMID 22363695, 2012). "Based on previous studies indicating a prognostic role for Gas6 in AML, we hypothesize that paracrine or autocrine expression of Gas6 (or other Mer ligands) by the leukemia cell itself or by the supportive marrow stroma, could serve as a clinical biomarker, however further investigation is needed." (PMID 25762638, 2015). "Our findings are consistent with the recent report showing that Gas6/AXL signaling stabilizes β‐catenin protein in an AKT‐dependent mechanism, thereby regulating self‐renewal of drug‐resistant leukemia stem cells." (PMID 30353671, 2018). "Moreover, AML cells overexpressing Axl were able to induce the expression of Gas6 in bone marrow stromal cells which acts on the Axl-expressing AML cells to induce proliferation, survival and chemoresistance in the leukemia cells." (PMID 28918518, 2017).
non-small cell lung carcinoma (12 papers, 2011 to 2026). A group of at least three distinct histological types of lung cancer, including non-small cell squamous cell carcinoma, adenocarcinoma, and large cell carcinoma. "Nuclear PD-L1, coupled with transcription factor Sp1, activates the MERTK signaling pathway by regulating Gas6 mRNA synthesis and promoting Gas6 secretion, which promotes cell proliferation in non-small-cell lung cancer (NSCLC)." (PMID 35907881, 2022). "Analogous this expression of Gas6 in macrophages was also observed in human samples of non small cell lung cancer." (PMID 27486820, 2016). "Because the receptor tyrosine kinase Axl and its ligand Gas6 could be involved in promoting non-small cell lung cancer (NSCLC), we investigated the role of Gas6 secreted by CAFs during chemotherapy in NSCLC." (PMID 28878389, 2017). "In non-small cell lung cancer, nPD-L1 can directly bind to the transcription factor SP1 and upregulate the expression of growth arrest-specific 6 (GAS6)." (PMID 37275876, 2023). "Similarly, in mesenchymal non-small-cell lung cancer cell lines with EMT features, resistance to erlotinib and upregulation of AXL was associated with markedly increased levels of GAS6.16, 17 Therefore, cleaved soluble GAS6 could be exploited as a biomarker of resistance to ALK inhibition." (PMID 26616860, 2016). "This study confirmed that survival after resection of a non-small cell lung cancer is significantly reduced when the TNM status is improved; in contrast, marked expressions of CD68 and Gas6 as biological markers of the tumour's inflammatory reaction were associated with a favourable outcome." (PMID 21794149, 2011).